MAG (myelin associated glycoprotein)
Diseases named in the same sentence as MAG in open-access papers (continued):
Sharing a sentence is not in itself a finding about the gene and the disease.
neurodevelopmental disorder (4 papers, 2020 to 2024). A behavioral and cognitive disorder with onset during the developmental period that involves impaired or aberrant development of intellectual, motor, or social functions. "Moreover, interesting risk factors for neurodevelopmental disorders were newly identified in the brain soluble fraction sheddome such as Neurofascin (NFASC), Myelin-associated protein (MAG), or Latrophilin 3 (ADGLR3), among others." (PMID 38962061, 2024). "Our findings demonstrate that DOP1A, as well as the DOP1A-MON2-kinesin-1 complex, could be new candidates for neurodevelopmental disorders due to the potential effect on PLP1 and MAG, which are critical to myelination, but that needs more laboratory-validation of functional and genetic evidence." (PMID 38818041, 2024).
psychiatric diseases (2 papers, 2024 to 2025). "Concordant with the increased inflammatory signal, there was a downregulation in mRNA expression of genes linked to neurodevelopment and myelination, neurotransmitter regulation, and psychiatric disorders including calcium binding Calb2 and S100b, as well as SNAP25, Pvalb, MAG, Olig1, and Olig2." (PMID 40059770, 2025).
genetic diseases (1 paper, 2024). "PMD and PMD-like diseases are rare genetic diseases that affect the central nervous system, specifically the myelin sheath and they were reported to be caused by variants in PLP1/MAG." (PMID 38818041, 2024).
metabolic disorders (1 paper, 2021). "Consistently, the results revealed that dysregulation of MAG, HOXB3, MYRF and PLP1 led to metabolic disorders of sphingolipid and glutathione, which contributed to the pathogenesis of PD." (PMID 33325158, 2021).
MAG also shares sentences with these, for which no sentence is quoted: Guillain-Barre syndrome (5 papers); cryoglobulinemia (4); amyloidosis (3); diabetes (3); POEMS syndrome (3); vascular dementia (3); allergies (2); Anxiety (2); cerebral amyloid angiopathy (2); Endocrinopathy (2); lupus (2); multiple myeloma (2); myasthenia gravis (2); rheumatoid arthritis (2); Spastic paraplegia (2); acute inflammatory demyelinating polyneuropathy (1); alcohol abuse (1); angioedema (1); arteriolosclerosis (1); autism spectrum disorder (1); autoimmune disorder of the peripheral nervous system (1); autosomal recessive cerebellar ataxia (1); B cell Lymphoma (1); bipolar disorder (1); brain injury (1); cerebellar ataxia (1); chronic lymphocytic leukemia (1); cleft palate (1); cold agglutinin syndrome (1); connective tissue diseases (1).
A further 52 diseases each share a sentence with MAG in 1 paper.